ALB (albumin)
Diseases named in the same sentence as ALB in open-access papers (continued):
Sharing a sentence is not in itself a finding about the gene and the disease.
cancer (continued). "This review highlights the recent methodologies for the fabrication of albumin-based nanoparticles, application of these nanoparticles in overcoming cancer drug resistance, and future perspectives and challenges." (PMID 35582218, 2020). "A solution towards a resistant form of cancer was proposed as inhalable self-assembled nanoparticles comprised of human serum albumin (HSA), tumor necrosis factor (TNF)-related apoptosis-inducing ligand (TRAIL) and Dox." (PMID 31973051, 2020). "ALB is an acute-phase protein regarded as a marker of systemic inflammation, which enabling ALB closely related to the occurrence and development of cancer." (PMID 32211311, 2020). "Along with in vitro studies showing that cancer cells can use albumin as an alternative source of nutrients, hypoalbuminemia was also seen in some cancer patients." (PMID 32175281, 2020). "Many researches have also found that a high CRP/ALB ratio is an independent prognostic marker for cancer patients." (PMID 31998420, 2020). "Hypoalbuminemia in cancer patients has been reported to result from a reduction in albumin synthesis mediated by secretion of pro-inflammatory cytokines, increased catabolism, and cachexia." (PMID 32974174, 2020). "Serum albumin level, which is commonly used to assess the nutritional status, is an important prognostic factor in advanced cancer." (PMID 32349713, 2020). "The systemic inflammation score (SIS), which is based on the pretreatment level of lymphocyte-to-monocyte ratio (LMR) and serum albumin (Alb), has been shown to be of prognostic value in a number of cancers." (PMID 33101044, 2020). "The levels of ALB, as an important nutritional factor, reflected the nutritional status in a variety of cancers." (PMID 32047540, 2020). "Due to the greater biodegradability and low immunogenicity of serum albumin, it has been identified as a suitable nanocarrier for the cancer management in recent years." (PMID 33321953, 2020). "Even though blood pressure inside the tumors is low due to high interstitial pressure, lymphatic deficiency and leaky blood vessels increase the accessibility of cancer cells to the blood serum or its main protein, albumin." (PMID 32175281, 2020). "Using select baseline clinical factors, including ECOG, hemoglobin, and albumin, we have created a concise nomogram to predict for cancer-related hospitalization among those receiving definitive doses of thoracic radiation." (PMID 32306924, 2020). "For example, albumin (ALB), which was listed in 10 proteome and three secretome studies, has been identified as a poor prognostic factor in cancer patients." (PMID 32197468, 2020). "At the same time, cancer can increase the expression of proinflammatory IL-6 and tumour necrosis factor-α and consequently decrease serum albumin, resulting in a vicious cycle." (PMID 33299415, 2020). "Studies have reported that baseline CRP and CRP/Albumin are independent prognostic factors for various cancer patients including NSCLC." (PMID 32181373, 2020). "ALB is considered to play a pivotal role in the inflammatory process and has been known as a prognostic indicator in several types of cancer." (PMID 32963562, 2020). "As compared to the CHD group, the DLD group was older, received less cumulative cisplatin dose, had an earlier cancer stage, had more comorbidities, and had higher baseline albumin levels." (PMID 32670072, 2020). "A recent study demonstrated greater drug delivery of albumin-conjugated cancer drug when combined with a collagen-binding domain." (PMID 33260517, 2020). "Albumin-to-globulin ratio has been reported as a prognostic factor in various disease conditions, including cancers." (PMID 33312698, 2020). "C-reactive protein, tumor necrosis factor, and interleukin-1 are involved in the pathogenesis of cancer, and can decrease serum albumin concentrations." (PMID 33215031, 2020).
cancer (continued). "KRAS-transformed cancer cells use macropinocytosis to internalize large proteins, such as albumin, from their extracellular environment, to subsequently break them down into amino acids, which enter the cell metabolism to promote cancer cell survival." (PMID 32807784, 2020). "Meanwhile, both high serum albumin level and low preoperative NLR also have been reported to be associated with better postoperative outcomes in several cancers." (PMID 32106833, 2020). "This score, based on the values of preoperative CRP and albumin, was found to have a high prognostic value in many cancer conditions." (PMID 33096884, 2020). "FcRn‐expressing cells would recycle the albumin‐drug conjugate, whereas cancer cells with a high metabolic intake due to FcRn underexpression would catabolize it and release the cytotoxic drug." (PMID 32368865, 2020). "The pretreatment serum albumin level in a cancer patient is generally used to assess nutritional status and predict prognosis." (PMID 31931816, 2020). "Studies have also identified the prognostic role of albumin-to-globulin ratio in predicting clinical outcomes and survival in cancers." (PMID 33312698, 2020). "Collectively, nanomedicine-based albumin drug delivery is a promising strategy to overcome cancer drug resistance." (PMID 35582218, 2020). "Recently, it has been reported that the pretreatment albumin-to-alkaline phosphatase ratio (AAPR) is related to the prognosis of various cancers." (PMID 33376729, 2020). "Serum albumin is a readily available parameter to evaluate patient’s nutritional status and provides useful prognostic significance in cancer survival and traumatic hip fractures." (PMID 32245389, 2020). "DOX/CCM albumin NPs blocked the adaptive treatment tolerance of cancer cells and elicited efficient cell killing." (PMID 31858848, 2020). "Albumin is an important drug carrier is gaining increasing importance in the target delivery of cancer therapy, particularly as a result of the market approval of the paclitaxel-loaded albumin nanoparticle, Abraxane40,41." (PMID 33110194, 2020). "Infections, burns, liver disease, nephrotic syndrome, and malignant tumors decrease serum albumin levels." (PMID 32974174, 2020). "The serum albumin level has been identified as a significant prognostic factor for patients with various types of cancer." (PMID 32760583, 2020). "Associations between blood transfusion, postoperative C-reactive protein (CRP), albumin, hemoglobin, complications, cancer-specific survival and overall survival (OS) were assessed using propensity score matching (n =116)." (PMID 31664621, 2020). "After adjusting for age, sex, BMI, and albumin, each unit of the ln-transformed FFA values generated a 35.8% risk of cancer [OR (95% CI): 1.358 (1.126, 1.638), P < 0.001]." (PMID 31773260, 2020). "The DLD group was older, had an earlier cancer stage, had more comorbidities, and had higher baseline albumin levels." (PMID 32670072, 2020). "First of all, the PNI, a combination of serum albumin and total lymphocyte count, reflects the link existing between immunity, inflammation, and nutrition in cancer, with their consequent potential prognostic implications." (PMID 32379785, 2020). "For example, thiol coated alginate-albumin nanoparticles were constructed using a coacervation method to deliver TAM to cancer cells." (PMID 32151063, 2020). "The GPS and mGPS are a combination of CRP and albumin scores, representing methods designed to predict the prognosis of cancer patients." (PMID 32974174, 2020). "It has been demonstrated that, for various types of cancer, the pretreatment albumin/alkaline phosphatase ratio (AAPR) was a prognostic factor." (PMID 32822383, 2020). "As an important nutritional factor, albumin (ALB) reflected the nutritional status in a variety of cancers." (PMID 32047540, 2020).
cancer (continued). "This review highlights the recent applications of albumin nanoparticles to overcome cancer drug resistance, the nano-fabrication techniques, as well as future perspectives and challenges." (PMID 35582218, 2020). "Recently, CRP and albumin with the Glasgow prognostic score (GPS) reported an independent prognostic value in patients with cancer." (PMID 32756384, 2020). "Meanwhile, the hepatic cells promote the production of acute-phase proteins, and reduce the production of albumin, especially among patients with advanced cancer." (PMID 33585198, 2020). "Cancer-related systemic inflammation, malnutrition, and an increased turnover of albumin by tumors can result in the inhibition of albumin synthesis and a reduction in serum albumin." (PMID 33215031, 2020). "The development of albumin-bound drugs is gaining increased importance in the targeted delivery of cancer therapy." (PMID 31858848, 2020). "In cancer patients, malnourishment and low serum albumin prior to anticancer therapy is a well‐established prognostic marker." (PMID 35847697, 2020). "Albumin nanoparticles show a better affinity for cancer treatment drugs such as doxorubicin, curcumin, Abraxane, and tacrolimus." (PMID 33027891, 2020). "A systematic review of 29 epidemiological studies showed that pretreatment ALB level is an independent predictor for patients’ survival, which is of great importance for evaluating the prognosis of cancer patients." (PMID 32691996, 2020). "A method that utilizes albumin as a carrier for cancer therapeutics involves drug encapsulation into an exogenous albumin-based particle." (PMID 31858848, 2020). "Low albumin levels reflect a decline in the status of nutrients, which is common in cancer patients, and is known to interfere with immune mechanisms such as humoral and cellular immunity and phagocytic function." (PMID 32974174, 2020). "Numerous studies have demonstrated the correlation of hemoglobin and albumin levels with OS in various cancers." (PMID 31167668, 2019). "Levels of CRP and albumin have been considered as possible prognostic factors of cachexia development for patient with cancers." (PMID 30941358, 2019). "In a univariate analysis age, sex, primary cancer type, albumin, and corrected calcium are shown to be significantly associated with survival, but the measured calcium was not." (PMID 31930179, 2019). "Serum CRP and albumin are indicators of chronic inflammation and poor nutritional status of cancer patients." (PMID 31644587, 2019). "Albumin as the major protein in circulation has been the focus of studies investigating how cancer cells co-opt macropinocytosis to acquire amino acids." (PMID 30967008, 2019). "Of the several factors examined, ECOG PS, clinical stage, certain cancer types (such as gastrointestinal cancer), serum albumin level, and specific organ disorder were shown to be significant background factors in the current univariate analysis." (PMID 30607523, 2019). "Other important biological characteristics of albumin include its accumulation at sites of inflammation from leaky capillaries and its active uptake by cancer cells, making it useful for targeting disease in molecular cancer therapeutics." (PMID 31520415, 2019). "Endogenous albumin was also harnessed to develop a more effective cancer vaccine exploiting the long circulation time of this protein, as well as its continuous perfusion of the lymph nodes." (PMID 31195727, 2019). "The results of the current study suggested that serum albumin level and comorbidity index are the principal clinical factors affecting therapeutic outcomes in elderly cancer patients receiving chemotherapy." (PMID 30607523, 2019). "Albumin is recognized as not only a marker of host-related nutritional status but also a marker of inflammation in patients with various types of cancer." (PMID 30974894, 2019).
cancer (continued). "This discrepancy was probably due to the fact that albumin was capable of binding glycoprotein 60 receptor around liver tumor epithelium and of enhancing the anti-cancer effect by targeted delivery." (PMID 31022951, 2019). "Previous studies showed that lower serum albumin level or albumin-based markers were independent predictors of poor survival in several cancers." (PMID 31612101, 2019). "Of note, albumin uptake by cancer cells has been also demonstrated and used as means to transport potential drugs formulated, e.g. as the albumin nanoparticles." (PMID 30765725, 2019). "Smoker and ex-smoker status and a history of cancer showed significant correlations with low serum albumin levels and a low BMI." (PMID 31196057, 2019). "Advanced cancer stage, older age, higher serum bilirubin levels, lower serum albumin levels, uncertainty of disease process, pain, fatigue, nausea, and poor performance status all have been identified as factors negatively affecting QoL." (PMID 31234316, 2019). "A complex interplay between changes in albumin degradation rates, increased capillary permeability, and decreased hepatic synthesis seems to be responsible for low serum albumin levels in cancer patients." (PMID 30535923, 2019). "Serum albumin, the most abundant protein in human serum, has been well documented as having inhibitory effects on cancer cell growth." (PMID 31683821, 2019). "Low body weight and hypoproteinemia are also both associated with persistent systemic inflammation, and the BMI and ALB have also been confirmed as effective prognostic markers for cancer patients." (PMID 31677642, 2019). "The other five factors that showed effects were baseline albumin (g/dL), neutrophil/lymphocyte ratio, baseline cancer antigen 19-9 (CA19-9, U/mL), disease stage at diagnosis, and body mass index (kg/m2)." (PMID 31357748, 2019). "Some in vivo and in vitro studies verified that the low LMR and decreased serum albumin were significant correction with the poor prognosis of the cancer patients." (PMID 31331297, 2019). "The prognostic nutrition index (PNI) is calculated based on the serum albumin concentration and peripheral blood lymphocyte count, and is an indicator of the nutritional and immune status of cancer patients." (PMID 32083015, 2019). "Several albumin-conjugated drugs and albumin-based nanoparticles have been reported for cancer diagnosis and therapy." (PMID 30626093, 2019). "Albumin is one key scavenged protein that has been shown to rescue cancer cells from amino acid starvation and to contribute to the free amino acid pool in pancreatic tumours." (PMID 30967004, 2019). "For treatments/applications that rely on the induction of oxidative stress, including cancer therapy, antibiotics, and antiviral treatment, we believe that albumin content should be considered." (PMID 31554226, 2019). "PIKfyve activity was shown to be required for amino acid scavenging from ingested apoptotic cells in macrophages, and also for the utilization of ingested albumin to support the proliferation of amino-acid-starved cancer cells." (PMID 30967004, 2019). "A simple, convenient, and highly sensitive bio-interface for graphene field-effect transistors (GFETs) based on multifunctional nano-denatured bovine serum albumin (nano-dBSA) functionalization was developed to target cancer biomarkers." (PMID 34137997, 2019). "Serum protein, albumin, hemoglobin, and eGFR levels were lower in cancer patients than in non-cancer patients." (PMID 31626671, 2019). "The first in vivo clues for the importance of extracellular proteins as nutrients for cancer cells came from the observation that rat carcinoma accumulates high levels of radioactively labelled albumin." (PMID 30967008, 2019). "Novelties such as Albumin-bound PTX(nab-PTX) are awesome examples of the progress in the oncology-associated area focused on cross-connection of nanotechnology and cancer treatment." (PMID 31783552, 2019).
cancer (continued). "In culture models, the pharmacological inhibition of PIKfyve activity largely blocks the pro-proliferative effects of mTOR inhibition, when the growth of various cancer cells is supported by albumin scavenging." (PMID 30967004, 2019). "Accumulating studies have demonstrated that FAR, cooperating albumin and fibrinogen, is an important prognostic predictor in various cancer." (PMID 31827921, 2019). "Studies have demonstrated that the Glasgow prognostic score (GPS), which is a simple and useful score and obtained using C-reactive protein (CRP) and albumin values is a practical tool in the determination of prognosis in many cancer types." (PMID 31096693, 2019). "Albumin catabolism even supports the proliferation of various cancer cells as well as fibroblasts expressing oncogenic Ras or PI3-kinase mutants in the complete absence of essential amino acids such as leucine." (PMID 30967008, 2019). "Second, when fatty acid-free media were supplemented with fatty acid-free albumin-complexed palmitate in order to facilitate its uptake by cancer cells, FASNlox/lox-PyMT, FASNlox/lox-HER2, or FASNlox/lox-KRAS MEFs did not form colonies in soft agar." (PMID 31676791, 2019). "Hemoglobin and albumin are two commonly used markers for nutritional status, which sharply decline during the progression of cancer." (PMID 31167668, 2019). "In our previous study, low preoperative albumin level and low BMI were indicative for 5-year mortality after free flap surgery for cancer of the head and neck." (PMID 30593593, 2019). "Recent published studies have reported that ALB was a nutritional factor, which reflected the nutritional status in several cancers, including EC." (PMID 31379941, 2019). "Preoperative serum albumin levels are also reported as prognostic indicators for the prognosis of cancer patients." (PMID 30116261, 2018). "In the validation cohort, data for age, BMIs, HDL, and Cu in both controls and cancer patients, serum total protein, albumin, and Cr in controls were normally distributed." (PMID 30586919, 2018). "The GPS is a selective combination of CRP and albumin serum levels that has been examined and validated in more than 60 studies for a variety of cancers." (PMID 29581844, 2018). "Serum albumin, known as an indicator of host inflammatory and nutritional status, had been verified its prognostic role in various types of cancers." (PMID 30564063, 2018). "For enhanced anti-cancer performance, human serum albumin fragments (HSAFs) nanoparticles (NPs) were developed as paclitaxel (PTX) carrier in this paper." (PMID 29946256, 2018). "Cancer patients are known to have relatively decreased plasma albumin levels when compared to healthy subjects." (PMID 30189620, 2018). "There are several albumin-bound drug delivery system was applied for cancer therapy such as Abraxane® with consideration of its commercial success." (PMID 29545617, 2018). "In those with advanced-stage (compared with early-stage) cancer, the albumin and HDL levels were significantly lower and the CRP level higher (p < 0.05)." (PMID 29941786, 2018). "Although it has been demonstrated that preoperative serum albumin is closely correlated with the prognosis of UC and other cancers, the latent mechanisms remain complex and unclear." (PMID 29685957, 2018). "Patients with HIVAMs were younger andpresented with earlier-stage cancers, but they had lower functional statuses andbiologic markers of health (hemoglobin, albumin) compared withnon–HIV-infected patients." (PMID 30241139, 2018). "This study aims to add to the ongoing discussion regarding the definition of cancer cachexia and to study the role of C-reactive protein and s-albumin in this context." (PMID 29534089, 2018). "Serum albumin and globulin levels are easily affected by dehydration and fluid retention, which are relatively common in cancer patients." (PMID 29300750, 2018).